RHOC (ras homolog family member C)
Description:
Regulates a signal transduction pathway linking plasma membrane receptors to the assembly of focal adhesions and actin stress fibers. Serves as a microtubule-dependent signal that is required for the myosin contractile ring formation during cell cycle cytokinesis. Regulates apical junction formation in bronchial epithelial cells.
Synonyms: h9; ARH9; ARHC; RHOH9
Tractability: Small molecule: a structure with a bound ligand is known; it has a high-quality binding pocket. Antibody: UniProt places it where antibodies can reach, with high confidence; its Gene Ontology location is reachable by antibodies, with high confidence. PROTAC: ubiquitination databases record sites on it; its protein half-life has been measured; a small molecule that binds it is known.
Gene: Protein-coding gene on chromosome 1 (112,701,127 to 112,707,845, reverse strand). Ensembl gene ENSG00000155366.
Subcellular location: Cell membrane; Cleavage furrow
Pathways (Reactome):
Signal Transduction: G alpha (12/13) signalling events; RHO GTPases Activate Formins; RHO GTPases Activate ROCKs; RHO GTPases Activate Rhotekin and Rhophilins; RHO GTPases activate CIT; RHO GTPases activate PKNs; RHOC GTPase cycle
Developmental Biology: Sema4D induced cell migration and growth-cone collapse
Gene Ontology:
Molecular function: protein binding; protein kinase binding; G protein activity; GTP binding; GTPase activity
Biological process: apical junction assembly; mitotic cytokinesis; positive regulation of canonical NF-kappaB signal transduction; positive regulation of cell migration; positive regulation of lipase activity; positive regulation of stress fiber assembly; actin filament organization; cell migration; positive regulation of protein-containing complex assembly; regulation of actin cytoskeleton organization; skeletal muscle satellite cell migration; wound healing, spreading of cells; small GTPase-mediated signal transduction
Cellular component: cleavage furrow; extracellular exosome; cytosol; endoplasmic reticulum membrane; plasma membrane; stereocilium; membrane; nucleus
Genetic constraint (gnomAD): Loss-of-function variants: 13 observed, 20.17 expected, observed/expected ratio (o/e) 0.64, 90% interval 0.42 to 1.02. The upper end of that interval is the gene's LOEUF score, 1.02, which puts it in group 4 of 6, group 1 being the genes least tolerant of losing a copy. Missense variants: 173 observed, 269.49 expected, observed/expected ratio (o/e) 0.64, 90% interval 0.57 to 0.73. Synonymous variants: 106 observed, 103.33 expected, observed/expected ratio (o/e) 1.03, 90% interval 0.88 to 1.21.
Homologues: Orthologues: dog RHOC (100% identical), guinea pig RHOC (100% identical), mouse Rhoc (100% identical), pig RHOC (100% identical), rat Rhoc (99% identical), chimpanzee RHOC (97% identical), Drosophila melanogaster Rho1 (85% identical). Paralogues in human: RHOA (92% identical), RHOB (85% identical), RAC1 (56% identical), RAC2 (54% identical), RHOG (53% identical), RAC3 (53% identical), RHOQ (51% identical), CDC42 (50% identical), RHOD (50% identical), RHOF (49% identical), RHOJ (48% identical), RND3 (47% identical), and 10 more.
Diseases named in the same sentence as RHOC in open-access papers:
RHOC is named in the same sentence as 87 diseases in open-access papers, as found by Europe PMC text mining. Sharing a sentence is not in itself a finding about the gene and the disease. The quoted sentences say what the papers report.
breast carcinoma (68 papers, 2005 to 2025). "RhoC was selected because it has been found to be expressed in a variety of tumors, such as liver, gastric, ovarian, and breast cancer; in addition, it is associated with the invasion and metastasis of tumors." (PMID 28818073, 2017). "RhoC is a key protein that mediates the cell shape and motility and is implicated in the aggressiveness of breast cancer." (PMID 26655092, 2016). "The other purpose of the study is to establish a causal relationship between RhoC expression and in vitro invasiveness of breast cancer cells." (PMID 29147173, 2010). "Using the cells thus generated we have shown that loss of RhoC in the breast cancer cell MDA-MB-231ΔRHOC is accompanied by the significant reduction in invasiveness of breast cancer cells in vitro." (PMID 29147173, 2010). "Over-expression of RhoC has been observed in the most aggressive form of breast cancer, inflammatory breast cancer, and is directly implicated in the control of the production of angiogenic factors in inflammatory breast cancer cells." (PMID 29147173, 2010). "Finally, a tissue microarray of breast cancer samples from 136 patients indicated a high correlation between RhoC and ALDH1, further supporting RhoC’s association with ALDH." (PMID 31340863, 2019). "In breast cancer, overexpression of RhoC is linked with poor prognosis." (PMID 29152087, 2017). "Increased RhoC expression has been claimed as the possible cause for the induction in invasion and metastasis triggered by the overexpression of the microRNA-10b in breast cancer." (PMID 20822528, 2010). "Therefore, Rho GTPases can contribute to the acquisition of a stem-like phenotype, and, since they are linked, ALDH activity could be a readout for RhoC activity in breast cancer." (PMID 32992837, 2020). "RhoC overexpression also enhanced mammary tumor formation in an activated Pik3ca model for breast cancer (Pik3caH1047R)." (PMID 38807216, 2024). "In RhoC-Pik3caH1047R mammary tumors, a shift in tumor histology was noted (in comparison to tumors that formed in control Pik3caH1047R model mice)." (PMID 38807216, 2024). "In vivo, knockout of RhoC in the Polyoma Virus Middle T mouse model reduces metastatic invasion of mammary tumors." (PMID 38807216, 2024). "RhoC was involved in the invasion and metastasis of breast cancer, lung cancer, pancreatic cancer, gastric cancer, and other malignant tumors." (PMID 36710485, 2023). "In breast cancer cells, the HOTAIR level is decreased following Ras homolog gene family member C (RhoC) knockdown via siRNA transfection, and Rho-associated protein kinase (ROCK) works as the intermediate effector." (PMID 34073224, 2021). "In breast cancer, RhoC expression correlates with increasing breast cancer stage and grade (as a histologic surrogate for aggressiveness), and higher RhoC expression was associated with higher patient mortality." (PMID 34513691, 2021). "This study reported that two breast cancer cell lines were transfected with a specific anti-RhoC GTPase, following this, the authors observed an increase in the expression of KAI1." (PMID 34121877, 2021). "Knockdown of Hop results in decreased RhoC levels in breast cancer cells, notably inhibiting the formation of filopodia." (PMID 34627249, 2021). "This study aims to investigate the role of RhoC in regulating cell-cell junction stability and interferon signaling in aggressive breast cancer cell lines." (PMID 34513691, 2021). "Of note, we created crRhoA and crRhoC breast cancer cell lines and found that knocking out RhoC resulted in increased expression of RhoA while knocking out RhoA resulted in a smaller magnitude increase in RhoC expression." (PMID 34513691, 2021).
breast carcinoma (continued). "RhoC is overexpressed in the majority of cases of inflammatory breast cancer, the most aggressive and metastatic form of breast cancer." (PMID 34513691, 2021). "It has been shown that RhoA and RhoC are overexpressed in various cancers, including breast cancer, lung cancer, and melanoma, and are correlated with tumor metastasis." (PMID 33406809, 2021). "This group found that RhoC expression was positively correlated with ALDH expression, and later identified RhoC as a potential direct regulator of ALDH expression in breast cancer cells." (PMID 32992837, 2020). "In further support of the oncogenic effect of RhoC, siRNA silencing of RhoC decreased breast cancer migration and invasion." (PMID 32992837, 2020). "Cdc42 is inhibited by StarD13 but it remains active at sites of invadopodia, where Cdc42 is required for activating nucleation promoting factors in a similar way to the spatial regulation described for RhoA and RhoC in breast cancer cells (model)." (PMID 32900380, 2020). "In contrast to RhoA and RhoB, research is more conclusive on the enhancing effects of RhoC on breast cancer migration and invasion." (PMID 32992837, 2020). "For instance, miR-509 was shown to be downregulated in brain metastases and promotes breast cancer cell invasion by upregulating RhoC/MMP9 and TNFα." (PMID 33002044, 2020). "RhoC has been shown to regulate angiogenesis in breast cancer, where it modulates the expression of VEGF, fibroblast growth factor-basic (bFGF), interleukin-6 and interleukin-8, which are important in angiogenesis." (PMID 31340863, 2019). "Our previous work demonstrated that the Rho-GTPases are potent regulators of macrophage-induced migratory responses; therefore, we examined M2a-mediated responses in RhoA or RhoC knockout breast cancer cell models." (PMID 31214501, 2019). "Two years later, the same group reported that RhoC was up-regulated in breast cancer samples post chemotherapy treatment, indicating increased RhoC levels in the chemoresistant population." (PMID 31340863, 2019). "This group went on to further design “smart” nanoparticles that delivered anti-RhoC siRNA into breast cancer cells, thereby successfully impeding migration and invasion." (PMID 31340863, 2019). "There is only one report which indicates the presence of RhoC in nuclear compartment in breast cancer cell lines." (PMID 31488179, 2019). "This process leads to increased RhoC expression, resulting in increased invasion and metastasis of breast cancer." (PMID 31340863, 2019). "Despite evidence for RhoA and RhoC contributing to breast cancer tumorigenesis and metastasis, RhoA subfamily GEFs that contribute to breast cancer in vivo have not yet been identified." (PMID 29769144, 2018). "Rac1, RhoA, and RhoC are commonly overexpressed in human breast cancers and RNAi-mediated knockdown or deletion of these genes inhibits tumorigenesis and metastasis." (PMID 29769144, 2018). "Here, we aim to compare the function of RhoC and its homolog family member RhoA in breast cancer progression." (PMID 29152087, 2017). "To obtain more insight into the role of RhoA and RhoC in the development of human breast cancer, we established stable cell lines whose expression of RhoA or RhoC can be induced reversibly." (PMID 29152087, 2017). "In breast cancer, RhoA and RhoC are both over-expressed and knockdown of each isoform decreased cell proliferation, migration and invasion in TNBC cell line MDA-MB-231." (PMID 27487152, 2016). "In conclusion, these results suggest that miR-10b stimulates the expression of c-Jun in metastatic breast cancer cells through RhoC and NF1." (PMID 27494896, 2016). "Recently, MKL and SRF were shown to play a key role in metastasis in melanoma and breast cancer xenograft systems providing a strong link to the transcriptional effects of RhoA or RhoC in these processes." (PMID 27600078, 2016).
breast carcinoma (continued). "Chronic ethanol exposure can increase the aggressiveness and CSCs of breast cancer cells via p38γ MAPK/RhoC signalings." (PMID 27557511, 2016). "RhoC siRNA effectively inhibited ethanol-induced migration and invasion, confirming that it played a critical role in ethanol-induced aggressiveness of breast cancer cells." (PMID 26655092, 2016). "We showed here that alcohol selectively activated p38γ MAPK and its down-stream effector, RhoC, resulting in enhanced aggressiveness of breast cancer cells." (PMID 26655092, 2016). "This suggests that p38γ and RhoC pathway plays an important role in ethanol-promoted aggressiveness of breast cancer." (PMID 26655092, 2016). "RhoC is highly over-expressed in inflammatory breast cancer, arguably the most aggressive form of breast cancer." (PMID 27600078, 2016). "We demonstrated that RhoA and RhoC are PFI targets that are essential for the invasive potential of breast cancer cells." (PMID 24587105, 2014). "Accordingly, Rho proteins, in particular RhoA and RhoC, play critical roles in tumor invasion and metastasis in a variety of cancers including breast cancer." (PMID 24587105, 2014). "Taken together, the data support a mechanism by which AGOH inhibits the invasive potential of breast cancer cells, at least in part, through inhibition of RhoA and RhoC activity." (PMID 24587105, 2014). "Collectively, the data further demonstrated that RhoA and RhoC are targets of PFIs in breast cancer cells." (PMID 24587105, 2014). "Dysregulation of small GTPases such as Ras and Rho family GTPases (RhoA, RhoC, Rac1 and Cdc42) is critical to drive the invasion and metastasis of a variety of cancers, including breast carcinomas." (PMID 24587105, 2014). "The relationship between RhoC and BCSCs persists in breast cancer patients, as expression of RhoC and the BCSC marker ALDH1 are highly correlated in clinical specimens." (PMID 22911725, 2012). "Clinically, RhoC expression increases with breast cancer progression, and high RhoC expression is significantly associated with decreased patient survival." (PMID 22911725, 2012). "Expression of RhoC and ALDH1 were strongly positively correlated in the 136 samples analyzed, indicating a tight association between RhoC and a BCSC marker in breast cancer patients." (PMID 22911725, 2012). "Cellular projections that promote matrix degradation are termed invadopodia and Rgnef localizes around these sites to activate RhoC in breast carcinoma cells." (PMID 22649559, 2012). "RhoC GTPase expression and activation is suggested to influence the breast cancer stem cell phenotype." (PMID 22046561, 2011). "The breast cancer cell line MDA-MB-231 was transfected with either a retroviral RhoC transgene or a control retroviral transgene." (PMID 29147173, 2010). "We have previously reported a correlation between nodal involvement and metastasis with raised levels of RhoC, RhoG and Rho6 in breast tumor tissue together with significantly higher levels of RhoC and RhoG in patients who died of breast cancer." (PMID 29147173, 2010). "RhoC is upregulated in many cancers including breast cancer and squamous cell carcinoma (SCC) of skin." (PMID 20822528, 2010). "In this study, we have utilised ribozyme transgene technology to knock down the expression of RhoC in breast cancer cells in order to assess the impact of targeting RhoC on cancer cell invasion." (PMID 29147173, 2010). "In breast cancer studies, RhoC has been identified as a highly specific marker in detecting tumors that developed metastases." (PMID 29147173, 2010). "This study aims to investigate the impact of targeting RhoC in human breast cancer cells by utilising ribozyme transgene technology and to assess its effect on cancer cell invasion." (PMID 29147173, 2010). "In conclusion, this study has shown that eliminating the expression of RhoC by ribozyme technology in MDA-MB-231 breast cancer cells reduces their in vitro invasiveness compared with wild type MDA-MB-231 cells." (PMID 29147173, 2010).
breast carcinoma (continued). "Our study has shown that the U1 promoter is sufficient in driving the expression of the anti-RhoC transgenes, resulting in an almost completely knocking down of the gene transcript in the breast cancer cells." (PMID 29147173, 2010). "In this study, our results suggested that the effect of PRDX6 on the invasive and metastatic potential of breast cancer cells was mediated partially through regulation of RhoC expression." (PMID 17980029, 2007). "Our laboratory has previously demonstrated that RhoC can mediate inflammatory breast cancer cell migration and invasion through co-activation of the p42/p44 Erk and p38 arms of the MAPK pathway." (PMID 15969750, 2005). "Consistent with this, upregulated expressions of RhoA and RhoC have been reported in breast cancer." (PMID 40214422, 2025). "The authors further demonstrated that the inhibition of the proliferation and invasion of SUM149 and SUM190 breast cancer cells by RhoC knockdown was via the increase of KAI1 (a tumor metastasis suppressor) and decrease of CXCR4 (a tumor progression promoter) and MMP9." (PMID 40214422, 2025). "Notably, recent studies have identified a novel isoform of ATOH8, ATOH8-V1, which was highly expressed in breast cancer and promoted metastasis by regulating RhoC." (PMID 40282270, 2025). "Likewise, miR-509 targets TNFα and RhoC in breast cancer BM which inhibits RhoC-induced MMP-9 activity, disrupting tight junctions in the BBB." (PMID 38194195, 2024). "Indeed, RhoC overexpression dramatically increased mammary tumor formation induced by NeuNT and Pik3caH1047R." (PMID 38807216, 2024). "Although we found variabilities along the stages, which reflects the heterogeneity of this disease, COMMD4_AS2, MARK3, MATR3, POLDIP3, COMMD4_AS1, and GNAS underwent AS switches in almost all stages of breast cancer, while RHOC displayed significant AS switches during stage IIB." (PMID 36725888, 2023). "For example, regulation of RhoC/ROCK1/MAPK axis likely alters breast cancer cell progression." (PMID 35179516, 2022). "Thus, we set out to study how RhoA- and RhoC-GTPase influence the cell-cell junctions in aggressive breast cancers." (PMID 34513691, 2021). "Previous work from our lab has identified RhoC as a modulator of stemness markers in breast cancer cells, and moreover identified RhoC as necessary for lung metastasis from orthotopic xenografts while increased stemness markers modulated the number of metastases." (PMID 34513691, 2021). "Another study showed that the dominant negative mutant of RhoC significantly reduces the actin polymerization induced by myosin-interacting guanine nucleotide exchange factor (MyoGEF), and inhibits the polarity and invasive activity of breast cancer cells." (PMID 34627249, 2021). "RhoC can regulate the formation of protrusions in many cells, and its expression and regulation has been proven in human macrophages, as well as prostate cancer, colorectal carcinoma, and breast cancer cells, respectively." (PMID 34627249, 2021). "As such, via multiple mechanisms, our data indicate that the inhibition of RhoC in aggressive breast cancers could provide anti-invasion therapeutic benefit." (PMID 34513691, 2021). "To investigate whether RhoA and RhoC expression affect the invasive potential of breast cancer cells, we conducted transwell invasion assays." (PMID 34513691, 2021). "RhoC, a member of the Rho GTPase family, has been shown to facilitate metastasis of aggressive breast cancer cells by influencing motility, invasion, and chemokine secretion, but as yet there is no integrated model of the precise mechanism of how RhoC promotes metastasis." (PMID 34513691, 2021). "The cell lines we focused on in this study are both triple-negative breast cancers, and the RNAseq results of decreased ISG expression in RhoC knockout cells compared to wild-type were more significant in our triple-negative breast cancer cell lines than in other breast cancer cell lines." (PMID 34513691, 2021).